VWF (von Willebrand factor)
Diseases named in the same sentence as VWF in open-access papers (continued):
Sharing a sentence is not in itself a finding about the gene and the disease.
COVID-19 (continued). "Objective: to provide a rationale for the role of pulmonary vascular endothelial VWF in thrombus formation in COVID-19." (PMID 35215805, 2022). "Further proof-of-concept that C5a has thrombogenic effects on endothelial cells comes from data showing that C5a inhibition halts the platelet aggregation induced by sera from severe COVID-19 patients, possibly through the exocytosis of vWF and P-selectin." (PMID 35320941, 2022). "For instance, vWF was significantly increased in the plasma of hospitalized COVID-19 patients indicating endothelial activation and a prothrombotic state in severely ill patients." (PMID 35242762, 2022). "Patients with COVID-19 had significantly higher levels of von Willebrand Factor antigen when compared to the control group (288.3 [± 80.26] % vs. 212 %; p = 0.0469)." (PMID 34904186, 2022). "In COVID-19, multiple hemostatic pathways can be affected, including primary hemostasis (platelets and von Willebrand factor [VWF]), secondary hemostasis (‘coagulation’), and fibrinolysis." (PMID 35225866, 2022). "The results of the study demonstrated an important role of endothelial VWF in the pathogenesis of pulmonary vascular thrombosis in COVID-19." (PMID 35215805, 2022). "The increase in VWF factor in plasma, in combination with reduced level of metalloproteinase responsible for its cleavage, were found not only in COVID-19, but also in community-acquired pneumonia." (PMID 35215805, 2022). "Circulating concentrations of C-reactive protein, ferritin, D-dimers, fibrinogen, Factor VIII and von Willebrand factor were higher in the post-COVID-19 group at enrollment compared to the control group, consistent with hemostatic pathway activation." (PMID 35606551, 2022). "Moreover, it has been established that considerable hypoxaemia in COVID-19 patients is caused in prothrombotic conditions through stimulation of endothelial synthesis of procoagulants, upregulation of plasminogen activator inhibitor and releasing tissue factor and VWF as well." (PMID 36128671, 2022). "COVID-19 is characterized by other coagulation abnormalities, such as a dramatic increase in thrombin production and elevated concentrations of both von Willebrand factor and factor V." (PMID 36292069, 2022). "Von Willebrand factor/ADAMTS13 ratio has been found impaired in COVID-19 patients outside pregnancy." (PMID 35189860, 2022). "Our prospective data from an all-comers cohort accentuates vWF antigen as a distinct feature of COVID-19 and add to the amounting evidence linking activation of CS with vWF antigen and endothelial damage." (PMID 34904186, 2022). "Taking into account that the in vivo biosynthesis of von Willebrand factor is restricted to endothelial cells and megakaryocytes, high plasma von Willebrand factor concentrations in patients with COVID-19 suggest significant endothelial cell injury." (PMID 36292069, 2022). "A considerable elevation of factors v, viii; and VWF has also been indicated in intense COVID-19 patients." (PMID 36128671, 2022). "A number of studies have reported an imbalance of VWF and ADAMTS-13 in COVID-19 patients, which is associated with a high thrombotic risk." (PMID 35215805, 2022). "Recent studies have also reported that the VWF circulating concentration is highly related to COVID-19 severity." (PMID 35634344, 2022). "This included elevation in convalescent COVID-19 patients versus healthy controls of von Willebrand factor (vWF) antigen, vWF propeptide, and soluble thrombomodulin." (PMID 35912863, 2022). "A recent study using artificial intelligence techniques revealed that genes involved in activation of immune pathways (IL-6, TNF, JAK2, IL-1B, SERPINE1, TGFB1, CD8A, and VWF) serve as major hubs in the COVID-19- thrombocytopenia interactomes." (PMID 35372456, 2022). "In the course of COVID-19, ADAMTS13 activity decreases, which is associated with an increase in VWF activity and a higher thrombotic risk." (PMID 36551272, 2022).
COVID-19 (continued). "We have proven that a decrease in the level and activity of ADAMTS-13 in patients with severe COVID-19 can lead to an imbalance between vWF and ADAMTS-13." (PMID 35887770, 2022). "Elevated vWF activity (3 times to 4 times the upper limits of the normal range) in a COVID-19 patient suggests the presence of severe endothelial stimulation and damage." (PMID 35111367, 2022). "Regarding platelet activation, Von Willebrand factor (vWF) and prothrombin (F2) were downregulated in the COVID-19 group." (PMID 35842415, 2022). "It is possible that the imbalance between VWF levels and ADAMTS13 contributes to the thrombosis caused by COVID-19." (PMID 36142094, 2022). "VWF was significantly (p < 0.0001) elevated in COVID-19 patients compared to healthy controls and correlated (p < 0.05) to ANGPT2." (PMID 35740360, 2022). "We present clinical and laboratory features, outcomes and data on vWF ADAMTS 13 axis obtained in a cohort of pregnant women with COVID-19 consecutively admitted to two Academic Hospitals in Southern Italy." (PMID 35189860, 2022). "There was a significant correlation between CS C3 and 5a with vWF antigen (rs = 0.5957 [p = 0.0131] and rs = 0.5015 [p = 0.042]) in COVID-19 patients." (PMID 34904186, 2022). "COVID-19 patients had significantly higher levels of vWF antigen when compared to the control group (288.3 [± 80.26] % vs. 212 %; p = 0.0469)." (PMID 34904186, 2022). "Von Willebrand Factor (vWF), a major marker of endothelial cell dysfunction, was found to be significantly elevated in laboratory examination of COVID-19 patients, and its value was positively correlated with the severity of the disease." (PMID 35990983, 2022). "According to literature reports, COVID-19-associated hypercoagulable state is characterized by elevated levels of D-dimer, fibrinogen, factor VIII (FVIII), and von Willebrand factor (vWF), together with reduced ADAMTS-13 activity." (PMID 35757331, 2022). "The important role of VWF in the pathogenesis of thrombosis in COVID-19 was proved by significantly higher intensity of IHC reaction in pulmonary vascular endothelium of patients with thrombosis compared to patients with PE." (PMID 35215805, 2022). "The important role of VWF in thrombosis development in COVID-19 was supported by significantly more intensive VWF immunostaining in pulmonary vessel endothelium of patients with thrombotic complications than the patients without thrombotic complications." (PMID 35215805, 2022). "Together with VWF, D-dimer and complement activation status are considered prognostic indicators of adverse outcomes of COVID-19." (PMID 35588457, 2022). "A high level of high-molecular-weight VWF multimers in the blood of critically ill COVID-19 patients has been reported." (PMID 35215805, 2022). "COVID-19 patients generally show increased levels of vWF and Factor VIII, which both promote venous thromboembolism (VTE) events." (PMID 35458574, 2022). "Even though in COVID-19 patients there are alterations in D-dimers, fibrinogen and vWF, the levels of PT and aPTT stay relatively normal." (PMID 36295093, 2022). "It was also found that Von Willebrand factor antigen concentrations were higher than normal in COVID-19 ICU patients." (PMID 35168674, 2022). "Injured endothelial cells also play a critical role in microvascular thrombosis in COVID-19, since these cells produce ultra-large von Willebrand factor (VWF)." (PMID 35908022, 2022). "Since most COVID-19 coagulopathy patients display autoantibodies against vWF, PDE and PF4 along with CL, combinations of viral and bacterial infections appear to be necessary to initiate their autoimmune coagulopathies." (PMID 36232795, 2022). "Compared to healthy control subjects, cirrhotic patients and COVID-19 patients exhibited markedly increased VWF antigen, while the highest median VWF antigen level occurred in ARDS-COVID patients." (PMID 34945736, 2021).
COVID-19 (continued). "It is well possible that the highly elevated FVIII:C levels, paralleling the increased VWF values in COVID-19 are equally or more relevant in mediating a prothrombotic effect." (PMID 33572417, 2021). "This article attempts to highlight several commonalities between DCI and COVID-19, namely, endotheliopathy, derangement in the von Willebrand Factor (vWF)-platelet axis, and microthrombosis." (PMID 34208470, 2021). "This study also reports on VWF multimer accumulation in the plasmas of COVID-19 (+) patients suggesting a relationship between endothelial coagulation and COVID-19 disease severity." (PMID 35087853, 2021). "Von Willebrand factor, an acute-phase coagulation protein, has been shown to be 5- to 10-fold elevated in symptomatic COVID-19 patients." (PMID 33806540, 2021). "Alteration of vascular structures was further demonstrated by immune-staining of alpha-smooth muscle actin (αSMA) and von Willebrand factor (vWF) as compared to control livers from non-COVID-19 patients." (PMID 34064487, 2021). "In patients <65 years of age, significant increases in median VWF:AG and VWF:CBA levels in COVID-19 (+) patients were observed." (PMID 35087853, 2021). "COVID-19 patients show a broad spectrum of endothelial alterations, such as an increase in the activity of coagulation factor VIII and a high increase in von Willebrand factor and angiotensin II level in the plasma, associated with viral load and lung damage." (PMID 34001199, 2021). "This retrospective analysis of acutely ill COVID-19 (−) and COVID-19 (+) patients suggests VWF/ADAMTS13 axis parameters, along with thrombin and plasmin generation, are relevant coagulation parameters to measure in early COVID-19 infection." (PMID 35087853, 2021). "This relationship was significant in both groups (ICU: p = 0.006; MW: p = 0.02).Conclusions: The present findings show that in COVID-19, the VWF/ADAMTS-13 fraction predicts in-hospital mortality." (PMID 34573989, 2021). "We found that the expression of TM and vWF in interstitial vessels, glomerular, and tubules were higher in kidneys from COVID-19 patients who had died compared to those in kidneys from renal carcinoma patients." (PMID 34829436, 2021). "High levels of FVIII were found in the plasma of COVID-19 patients, and vWF levels were higher in the plasma of ICU hospitalized compared with non-severe COVID-19 patients." (PMID 34736472, 2021). "NETs have also been recently found in arterial microthrombi of post-mortem lung tissues of COVID-19 patients and it has been suggested that NETs binding to vWF provide a scaffold for platelet adhesion and thrombus formation." (PMID 34440201, 2021). "We found that the expression of TM and vWF, biomarkers of endothelium dysfunction, were increased in renal tissues from dead COVID-19 patients." (PMID 34829436, 2021). "A strong positive correlation was observed between von Willebrand factor antigen and plasma level of von Willebrand factor ristocetin cofactor activity in patients with severe COVID-19 (r = 0.966, p < 0.001)." (PMID 34940584, 2021). "Relative to the controls, the patients with severe COVID-19 had significantly higher concentrations of biomarkers for glycocalyx shedding (endocan and syndecan-1) and endothelial injury (vWF)." (PMID 34214123, 2021). "Here, we found that in the endothelium of decidua and chorionic villi of placentas derived from women with COVID-19, the expression of vWf is increased, being higher in severe cases, suggesting the existence of a thrombotic condition." (PMID 33578631, 2021). "On the other hand, significantly elevated VWF:AG, VWF:CBA and VWF:AG/ADAMTS13 activity ratios were observed in COVID-19 (+) patients." (PMID 35087853, 2021). "Studies have shown that patients with COVID-19 have significantly elevated levels of vWF antigen and activity, likely contributing to an increased risk of thrombosis." (PMID 34940584, 2021).
COVID-19 (continued). "A subset of COVID-19 inpatients presents a unique microangiopathy characterized by elevated VWF antigen and activity, D-dimer, schistocytes/RBC fragments, and evidence of macrothrombosis but also microthrombosis." (PMID 33709050, 2021). "Strikingly, all patients with COVID-19, displayed vWF-antigen levels above the cut-off, compatible with an acute-phase reaction." (PMID 33564744, 2021). "The hypercoagulable state observed in severe COVID-19 patients was associated with elevated levels of factor VIII and VWF, suggesting the involvement of endothelial cells." (PMID 34769508, 2021). "As a result of endothelial injury, sub-endothelial collagen exposure promotes innate adhesion of platelets to collagen through von Willebrand factor, which is vital in the adhesion process and significantly increased in COVID-19 patients." (PMID 33735911, 2021). "In a cohort of 150 elderly COVID-19 patients with a medical history of cardiovascular, respiratory, and multiple organ abnormalities, median VWF levels were reported at 455% of normal." (PMID 34575297, 2021). "Our results demonstrate upregulation of vWF and loss of thrombomodulin and EPCR in lung tissue from COVID-19." (PMID 34506304, 2021). "Levels of ADAMTS13, an antithrombotic metalloprotease which cleaves highly adhesive large von Willebrand factor (VWF) multimers after their release from activated endothelium, decreased significantly with increasing COVID-19 severity." (PMID 33058027, 2021). "Specifically, the median VWF:AG, and VWF:CBA levels in the COVID-19 (+) group were increased by 28.8% and 17%, respectively, compared to the COVID-19 (−) group (p < 0.0001; p = 0.002)." (PMID 35087853, 2021). "In the placenta of women with COVID-19, staining of vWf significantly increases in the decidual and chorionic villi endothelium." (PMID 33578631, 2021). "Considering the age-associated increase in VWF, it is plausible to hypothesize that elevated basal levels of VWF in elderly may increase their susceptibility towards development of CAC complications as a result of CoV-2 infection." (PMID 34575297, 2021). "Case series of critically ill COVID-19 patients have shown persistent severe elevation in VWF, fibrinogen, and factor VII, all of which are suggestive of endothelial injury." (PMID 33378321, 2021). "Respective median antigen and activity levels of VWF in the COVID-19 (+) group were 2.736 (IQR:1.822–4.060) and 3.745 (IQR:2.506–5.262) U/mL compared to 1.868 (IQR:1.257–2.770) and 2.989 (IQR:1.958–4.252) U/mL in the COVID-19 (−) group." (PMID 35087853, 2021). "For this purpose, we have studied the expression of vWf, claudin-5, and vascular endothelial (VE) cadherin in the decidua and chorionic villi of placentas derived from women with mild and severe COVID-19." (PMID 33578631, 2021). "Considering that the presence of A- or B-antigens in vWF N-linked oligosaccharides plays a role in vWF levels, reduction of the A- or B-antigen might be a reasonable approach for reducing plasma vWF levels as well as the risk of thrombopoietic symptoms of COVID-19." (PMID 33564039, 2021). "Despite elevated VWF function in COVID-19 (+) patients' plasma, only mild changes in ADAMTS13 levels or activity are observed." (PMID 35087853, 2021). "Our observations suggest that VWF:AG is increased in the plasma of both COVID-19 (−) and COVID-19 (+) patients at hospital presentation and admission." (PMID 35087853, 2021). "We performed a balanced retrospective study of COVID-19 hospitalized patients with similar demographics and comorbidities and a wide range of D-dimer levels to study how VWF biomarkers correlate with coagulation, intravascular hemolysis, and outcome." (PMID 33709050, 2021). "There is evidence that, in COVID-19 patients, the increase in VWF levels coexist with a moderate reduction in ADAMTS13 activity." (PMID 34977191, 2021).
COVID-19 (continued). "LSECs from liver autopsy samples from patients with COVID-19 expressed substantially higher levels of vWF and FVIII than LSECs from uninfected liver samples." (PMID 34291736, 2021). "VWF:AG, VWF:CBA and VWF:AG/ADAMTS13 activity were significantly increased in COVID-19 (+) patients within the overweight (25–29.9 kg/m2) and obese (>30 kg/m2) BMI groupings." (PMID 35087853, 2021). "High factor VIII, von Willebrand factor levels, and low protein S levels have been consistently reported in patients with COVID-19, but their role in the pathogenesis is unclear." (PMID 34476137, 2021). "Despite limited COVID-19 autopsy specimen availability, we observed increased levels of the prothrombotic endothelial protein vWF and decreased levels of antithrombotic endothelial proteins EPCR and thrombomodulin." (PMID 34506304, 2021). "The constituents of the clots arising in select COVID-19 patients are classic in comparison to existing literature, demonstrating an infiltration of NETs, citrullinated histones, and von Willebrand factor (vWF)." (PMID 34944683, 2021). "Consistent with histological evidence of clot formation with increased staining of VWF and fibrin, expression of genes associated with fibrin clot formation (FN1, FGA, and F13A1) was also increased in lung tissue from patients with COVID-19." (PMID 34648357, 2021). "We found peak D-dimer and vWF-ADAMTS13-platelet axis are associated with increased ICU severity and outcome in severe COVID-19 patients admitted to ICU." (PMID 34476137, 2021). "In patients with severe COVID-19, plasma levels of vWf antigen are increased, and in the placenta of healthy women, vWf has been found in endothelium, STB and chorionic villous stroma." (PMID 33578631, 2021). "In COVID-19, changes in prothrombotic factors like D-dimer, fibrinogen, factor VIII, and von Willebrand factor have been reported to cause a hypercoagulable state." (PMID 33628665, 2021). "Considering COVID-19, VWF antigen levels (VWF : Ag) and VWF : Ristocetin cofactor activity (VWF : RCo) have significantly increased in moderate and severe cases than in normal controls possibly without change in ADAMTS13 activity." (PMID 34912345, 2021). "We found vWF-ADAMTS13-platelet axis is associated with increased ICU severity and outcome in severe COVID-19 patients admitted to ICU." (PMID 34476137, 2021). "A significant increase in von Willebrand factor (VWF) in COVID-19 patients indicates a tendency towards platelet plug formation and thrombosis." (PMID 33806540, 2021). "During the late stages of COVID-19, VWF levels are indicative of depletion (clinical observation by co-author Laubscher) and this is due to large-scale endothelial damage." (PMID 32708334, 2020). "Fibrinogen, D-dimer, VWF and P-selectin are central in the development of coagulopathies, and coagulopathies with diverse aetiologies have been described in COVID-19 patients." (PMID 32708334, 2020). "Unusually high inflammatory and prothrombotic phenotype represents a striking feature of COVID-19 patients, as reflected by markedly elevated reactive protein C, fibrinogen, interleukin 6, von Willebrand factor, and factor VIII." (PMID 33488398, 2020). "A most important consideration for COVID-19 pathology, is that, under normal conditions, VWF is both a bleeding (when low) and thrombotic marker (when raised)." (PMID 32708334, 2020). "In this paper, we discuss the nexus between COVID-19 and circulating inflammatory biomarkers, with a particular focus on fibrin(ogen), its breakdown products (especially D-dimer), P-selectin and VWF." (PMID 32708334, 2020). "Specifically, dysregulation during COVID-19 has been noted in P-selectin, fibrinogen and D-dimers, and VWF." (PMID 32708334, 2020). "While elevated VWF predicts mortality in severe COVID-19, its relationship with post-discharge functional outcomes remains unclear." (PMID 41668981, 2026).